ATP7B (ATPase copper transporting beta)
Diseases named in the same sentence as ATP7B in open-access papers (continued):
Sharing a sentence is not in itself a finding about the gene and the disease.
Wilson disease (continued). "Many patients exhibit a spectrum of Wilson disease-like clinical symptoms, but upon gene sequencing, ATP7B or copper-metabolism pathways genes reveal no mutations." (PMID 38032054, 2024). "Wilson’s disease (WD), a rare disorder (MIM 277900; ORPHA:905), with a prevalence ranging from 1/30,000 to 1/50,000 and a relatively high carrier frequency of 1/90, is characterised by autosomal recessive mutations in ATP7B, a copper transporter." (PMID 39060521, 2024). "Copper contaminating food and drinking water can easily enter the human body, but generally does not harm healthy individuals as long as they are not compromised by ATP7B gene mutations that disturb copper homeostasis, like in Wilson disease." (PMID 38731973, 2024). "Besides Gaucher disease, the most common inherited metabolic disease gene carriers in our cohort are hyperoxaluria (AGXT; 1.1%, 18/1642), Wilson disease (ATP7B; 1%, 17/1642), and phenylketonuria (PAH; 0.79%, 13/1642)." (PMID 38167091, 2024). "Nevertheless, the search for ATP7B mutation is obligatory for a complete assessment in each patient with suspected Wilson disease but certainly restricted in countries lacking test availability or confronted with high costs." (PMID 38928368, 2024). "There are ongoing clinical trials of AAV-mediated gene transfer of ATP7B in humans, in which Wilson disease patients receive a single, peripheral intravenous infusion of UX701 or placebo, as outlined in detail by the US National Institute of Health (NIH) on their website, clinicaltrials.gov." (PMID 38731973, 2024). "Nevertheless, the search for ATP7B gene mutation is helpful for a complete assessment in each patient with suspected Wilson disease, a proposal restricted by current costs and lack of even availability worldwide." (PMID 38731973, 2024). "A negative result, however, does not exclude Wilson’s disease, as new mutations within the ATP7B protein coding gene have been detected." (PMID 38248841, 2024). "A knock out mice model of Atp7b was authorized for the Wilson disease model, as Cu accumulates." (PMID 38092388, 2023). "Mutations that result in a full absence or nonfunctional of ATP7B protein activity are rare and result in severe Wilson’s disease." (PMID 37048674, 2023). "Studies with Wilson disease model mice that accumulate excessive copper, due to a dysfunctional ATP7B “copper pump” resulting in decreased biliary excretion, showed that the compensatory increase in urinary copper loss was due to a small copper carrier (∼1 kDa) (SCC)." (PMID 35199838, 2022). "Besides, 12 subjects carried at least one high-risk recessive allele (12/27, 44.4%) either in ATP7B or in MUTYH gene, causative of Wilson disease and MUTYH-associated polyposis, respectively." (PMID 36437915, 2022). "The mechanism through which iron deposition occurs in Wilson’s disease is unknown; however, ATP7B is required for the biosynthesis of caeruloplasmin, a copper-dependent ferroxidase that plays an important role in iron metabolism." (PMID 34289020, 2022). "Hepatolenticular degeneration (HLD), also known as Wilson's disease (WD), is a genetic copper overload disease caused by inactivating mutations in the copper transporter P-type ATPase gene (ATP7B)." (PMID 35401189, 2022). "Copper transporter ATP7B is a copper-transporting ATPase that plays a central role in regulating copper homeostasis in the liver, and dysfunctional ATP7B is involved in the development of monogenic Wilson disease." (PMID 36568423, 2022). "The reason why only some patients with Wilson’s disease develop neurological involvement remains unclear despite concerted efforts to identify correlations with genotype and genetic modifiers in the ATP7B interactome." (PMID 34289020, 2022). "A serological evaluation for other causes of liver disease was negative including the ATP7B gene for Wilson disease." (PMID 34238237, 2021).
Wilson disease (continued). "Notably, the molecular genetic underpinnings of Wilson disease (OMIM 277900), a disorder of copper metabolism caused by deficiency of ATP7B, also differed considerably between populations." (PMID 34078906, 2021). "Human homeostatic iron regulatory protein (HFE) and ATPase copper transporting beta (ATP7B) germline gene mutations can cause chronic liver injury and progression into HCC by excessive iron (hemochromatosis) and copper (Wilson disease) accumulation in the liver, respectively." (PMID 33807605, 2021). "In this context, Cu2+ may also participate in CL decrease by catalyzing its fragmentation as was demonstrated in the Atp7b−/− mouse model of Wilson's disease." (PMID 34257827, 2021). "This idea is based mainly on the findings from the most well-studied disease of Cu overload (Wilson disease), first identified in humans and involving the “Cu pump” ATP7B, and on findings for Cu overload in dogs involving other proteins required for putting Cu into bile, namely COMMD1 and ABCA12." (PMID 32668621, 2020). "Due to their adjacent geographic locations, Korean, Japanese, and Chinese populations often share common mutations contributing to many autosomal recessive disorders, including c.648G > T of G6PC in glycogen storage disease type I [MIM #232200] and p.R778L of ATP7B in Wilson disease [MIM #277900]." (PMID 33176831, 2020). "In Wilson’s disease patients, copper is not removed properly due to mutations in the ATP7B gene that encodes the copper transporting P-type ATPase, which results in damages in several organs." (PMID 32252475, 2020). "Furthermore, hepatocytes derived from patients suffering from Wilson’s disease, as well as hepatocytes derived from Atp7b null mice and rats, contained elevated quantities of autophagosomes." (PMID 30609663, 2019). "Protein levels of RXR, not LXRα or LXRβ, are decreased in the liver of Atp7b-deficient mice, a model of Wilson disease." (PMID 31614590, 2019). "Since neutrophils from Wilson disease mice lack functional ATP7B, they might still be able to efflux excessive copper via ATP7A." (PMID 32010131, 2019). "The LEA rats were established from an outbred colony of Long-Evans rats, and were sometimes used as a control strain for the Long-Evans Cinnamon (LEC) rats, a rat model for Wilson’s disease, since they do not have the Atp7b mutation." (PMID 30591971, 2019). "Mouse lines KO for ATP7B have been studied and show progressive accumulation of Cu in the liver and liver pathology in adults animals, thus mimicking the main landmark of Wilson disease in human." (PMID 29954118, 2018). "Wilson’s disease (WD, OMIM #277900), an autosomal recessive disorder characterized by abnormal copper accumulation and related toxicities, is caused by mutations in the ATP7B gene (OMIM *606882)." (PMID 29649982, 2018). "Radionuclide 64Cu is a positron emitting copper isotope and 64CuCl2 was used as a radiotracer for noninvasive assessment of disturbance of cerebral copper fluxes in traumatic brain injury and age-dependent changes of copper fluxes in Atp7b-/- knockout mouse model of Wilson’s disease." (PMID 29392086, 2018). "We recommend genetic screening for ATP7A mutations in patients who manifest clinical symptoms of Wilson disease without mutations in ATP7B." (PMID 27878136, 2016). "Wilson's disease results from dysfunctional ATP7B, increased copper levels and altered redox state." (PMID 25870938, 2016). "ATP7B is the Wilson’s disease gene, and carriers have a slight increase in body copper load." (PMID 26633489, 2015). "The clinical architecture of Wilson’s disease results from interactions between ATP7B and a spectrum of other genetic modifiers, environmental or lifestyle and stochastic factors that could have a degree of population and geographic specificity." (PMID 24897373, 2014).
Wilson disease (continued). "Then, we briefly highlight key P-type ATPases involved in neuronal disorders such as the copper transporters ATP7A (Menkes disease), ATP7B (Wilson disease), the Na+/K+-ATPases ATP1A2 (familial hemiplegic migraine) and ATP1A3 (rapid-onset dystonia parkinsonism)." (PMID 24904274, 2014). "In addition, the well-known role of ATP7B in Wilson disease has been recently expanded to its involvement in other pathologies such as modulation of the Alzheimer’s disease phenotype and anticancer drug resistance." (PMID 24909901, 2014). "Our findings indicate that lysosomes serve as an important intermediate in ATP7B trafficking, whereas lysosomal exocytosis operates as an integral process in copper excretion and hence can be targeted for therapeutic approaches to combat Wilson disease." (PMID 24909901, 2014). "ATP7B is the gene product of the Wilson’s disease gene and is located on chromosome 13." (PMID 24378118, 2013). "In Wilson disease (WD), defective ATP7B-mediated hepatic copper clearance leads to systemic copper overload and markedly increased non-Cp Cu levels, sometimes exceeding 50–100% of total serum copper." (PMID 40563428, 2025). "Wilson disease (WD, OMIM 277900) is a hereditary metabolic disorder that disrupts copper homeostasis due to mutations in the ATP7B gene, which encodes the ATPase copper-transporting β protein." (PMID 40321812, 2025). "In bi-allelic genotypes, all these variants cause Wilson’s disease with recessive inheritance, but all carriers in the present study were heterozygous for these variants and our analyses revealed no additional variant in ATP7B in these individuals." (PMID 41465155, 2025). "Mutation analysis of the coding region of ATP7B (except exons 2, 3, and 21) performed in 150 patients with Wilson disease showed no detectable mutations in 15% of patients, and mutations causing the disease were found in 57% of patients on both chromosomes and in 29% of patients on one chromosome." (PMID 38731973, 2024). "The most common of these variants included both known high-frequency variants, such as the rs5030654 variant in PAH and the rs1555287300 in ATP7B linked to phenylketonuria and Wilson's disease, respectively, and variants that have not been previously reported as overrepresented." (PMID 39498263, 2024). "The multifaceted impact of Atp7b inactivation on ChPl and brain parenchyma during brain development offers new insight into Wilson disease (WD) pathogenesis." (PMID 36626371, 2023). "As for other membrane proteins such as CFTR (cystic fibrosis transmembrane conductance regulator) and ATP7B (copper-transporting ATPase 2), non-polar-to-polar missense variants in transmembrane domains destabilize the structure, leading to diseases such as cystic fibrosis and Wilson’s disease." (PMID 38066485, 2023). "Wilson disease (WD, OMIM: 277900) is a life-threating rare autosomal disorder of copper homeostasis, caused by pathogenic variants in the ATP7B gene, encoding for a P-type copper transporting ATPase mainly expressed in hepatocytes." (PMID 36092366, 2022). "The deletion of ATP7B in cells and animals could decrease copper toxicity in Wilson’s disease." (PMID 36405901, 2022). "Indeed, the Wilson disease-causing ATP7B-H1069Q mutation per se did not preclude trafficking of ATP7B to the TGN." (PMID 34360991, 2021). "These included two frequent polymorphisms whose impact on transcriptional activity was assessed with the idea that they may be able to modify Wilson disease phenotype in carriers of ATP7B mutations that are not fully inactivating." (PMID 33828154, 2021). "While neither polymorphism can be causative for Wilson disease due to their high prevalence, their location within the ATP7B core promoter potentially enables them to alter ATP7B transcription to some degree, similarly as has been observed for the D2 sequence variant." (PMID 33828154, 2021).
Wilson disease (continued). "Interestingly, the pharmacological inhibition of ATG7 and ATG13 accelerated cell death in the hepatoma cell line HepG2 when depleted for ATP7B expression, suggesting that autophagy protects against metal toxicity and copper-induced cell death in the setting of Wilson’s disease." (PMID 30609663, 2019). "Interestingly, that strong restriction of copper intake by Golgi complex leads to the same phenotype as in patients with Wilson disease, which develops from mutations in the ATP7B gene, but not in ceruloplasmin gene." (PMID 30959888, 2019). "Many different mutations in ATP7B may result in Wilson disease and there is a lack of a clear genotype-phenotype association." (PMID 26861285, 2016). "However, subcellular localization of these genes in Populus might change with varying metal supply, as seen in the mammalian Wilson's disease protein, ATP7B, which moves from the Golgi to the plasma membrane at higher metal concentrations." (PMID 26779188, 2015). "The Wilson disease (WD, OMIM 277900) is due to mutations in a copper transporter gene coding for the protein ATP7B that belongs to the P-type ATPase superfamily." (PMID 22046264, 2011). "To find new genes that might be targeted for reduction of Cu toxicity in Wilson disease we employed genome-wide shRNA screening in ATP7B-KO HepG2 cells, a bona fide WD cell model." (PMID 39922819, 2025). "Thus, a negative ATP7B does not rule out Wilson disease, and the conclusion may be drawn that Wilson disease can develop without an association with ATP7B." (PMID 38928368, 2024). "Thus, a negative screening results of ATP7B gene mutations do not rule out Wilson disease, and the conclusion may be drawn that Wilson disease can develop without an ATP7B gene-mutation association." (PMID 38731973, 2024). "The protection against Cu stress by standard Wilson disease therapeutics, i.e., D-Pen, trientine, and TTM, has been assessed on the parental HepG2/C3a cell line and two complete atp7b KO cell lines, sg1-1 and sg2-1." (PMID 36359796, 2022). "Wilson disease (WD), also known as hepatolenticular degeneration (HLD), is an autosomal recessive inherited disorder of copper metabolism, resulting from pathogenic mutations in the ATP7B gene." (PMID 34470610, 2021). "Considering that dysfunction of these transporters causes serious abnormalities of Cu homeostasis in Menkes and Wilson diseases, it would be extremely important to target ATP7A and ATP7B in a tumor-restricted manner." (PMID 31540259, 2019). "In order to determine the genetic prevalence of Wilson’s disease in French population, the promoter, the 5’UTR region, the 3’UTR region, all coding region and exon-intron junctions of ATP7B gene were sequenced in 697 DNA samples." (PMID 30097039, 2018). "Recent studies have demonstrated that transplantation of ATP7B-transduced hepatocytes ameliorates disease progression in LEC (Long-Evans Cinnamon) rats, a model of Wilson's disease (WD)." (PMID 25375371, 2014). "Glutaredoxin (thioltransferase), or GLRX, regulates the activity of the copper-transporting P-type ATPases ATP7A and ATP7B that are involved in Menkes disease (OMIM: #309400) and Wilson disease (OMIM: #277900), respectively." (PMID 21858011, 2011). "The likelihood of hereditary Wilson's disease was low, so we did not recommend sequencing the ATP7B gene." (PMID 38388441, 2024). "In addition to annotations to Wilson disease, experimental ChEBI annotations imported from CTD give evidence for interactions between copper and the mouse Atp7b protein." (PMID 34741192, 2022). "Although the ATP7B gene was negative, patient 5 was diagnosed with Wilson’s disease and was administered zinc acetate and trientine hydrochloride." (PMID 32942724, 2020). "In Wilson disease (with no functional ATP7B to incorporate Cu into ceruloplasmin), there still is Cu in the blood, and subjects lead relatively normal lives as long as they are treated with chelators to remove the excess Cu." (PMID 32668621, 2020).
Wilson disease (continued). "Upon comparing ATP7B genotype with clinical appearance and age at presentation of Wilson disease, no statistically significant changes were found." (PMID 28717664, 2017). "We identified the involvement of the copper transporter ATP7B in copper toxicosis in the Labrador retriever, identifying this breed as the first naturally occurring non-rodent mammalian model for Wilson disease." (PMID 26747866, 2016). "Wilson disease (WD; Online Mendelian Inheritance in Man [OMIM] accession number #277900) is an autosomal recessive copper storage disease resulting from biallelic pathogenic mutation in the ATP7B gene, which encodes the P-type adenosine triphosphatase (ATPase), ATPase-7B (OMIM number *606882)." (PMID 24368744, 2014). "The lack of ATP7B activity in patients with Wilson disease results in impaired copper loading to apo-Cp and in consequence in decreased Cp ferroxidase activity." (PMID 25247420, 2014). "Therefore, the negative effects of ATP7B inactivation on brain metabolism are evident in Wilson’s disease." (PMID 38956251, 2024). "However, the absence of ATP7B mutation and normal DNA copy number variant (CNV) ruled out Wilson disease." (PMID 35401690, 2022). "His initial workup was suggestive of Wilson disease—subsequent ATP7B gene was negative." (PMID 34238237, 2021). "al. have previously performed NMR spectroscopy on the homologous domain of the Wilson disease copper transporter, ATP7B, in the presence and absence of bound ATP and have derived from the resulting chemical shift data the residues important for ATP binding and hydrolysis." (PMID 19008952, 2008). "In summary, the investigations allowed to determine the biologically relevant site of ATP7B transcription initiation and demonstrated that genetic variations in this site, although being the focus of transcriptional activity, do not contribute significantly to Wilson disease pathogenesis." (PMID 33828154, 2021). "A liver-targeted AAV8-mediated ATP7B (AAV8-ΔC4ATP7B) gene therapy rescued impaired Cu metabolism and reversed liver histopathology without adverse effects in Atp7b R780L knockin (KI) mouse model, supporting the potential of AAV8-ΔC4ATP7B as a safe and effective treatment for Wilson’s disease." (PMID 40104154, 2025). "Finally, we showed that the absence of ATP7B leads to the impairment of the farnesoid X-receptor (FXR) at micromolar Cu concentrations, which is consistent with previously published data on Wilson disease." (PMID 36359796, 2022).